IL15 (interleukin 15)
Diseases named in the same sentence as IL15 in open-access papers (continued):
Sharing a sentence is not in itself a finding about the gene and the disease.
Obesity (continued). "Interestingly, other inflammatory markers, such as interleukin-15 (IL-15), tumour necrosis factor alpha (TNF-α), interferon gamma-induced protein 10 (IP-10), interleukin 6 (IL-6), and interleukin 8 (IL-8), correlated only with the microbiota profiles from children developing obesity." (PMID 30534614, 2018). "Since IL-15 is induced by inflammatory stimuli, and several inflammatory cytokines such as IL-6, TNFα, IFNγ are implicated in promoting obesity and insulin resistance, we postulated that IL-15 might contribute to the pathogenesis of obesity rather than conferring protection against it." (PMID 27684068, 2016).
breast carcinoma (72 papers, 2010 to 2026). "On the other hand, TRIB1 was found to be overexpressed by tumor-associated macrophages in breast cancer, and eventually reduced T cell infiltration by inhibiting IL-15, having immune-resistant underpinnings." (PMID 39513892, 2024). "Previous findings have described IL-7 as fundamental for the activation of myeloid cell populations in mice bearing CT26 tumors and for tumor invasiveness in prostate cancer, while IL-15–dependent signaling in tumor-associated macrophages inhibited CD8+ T cell recruitment in breast cancer." (PMID 39841829, 2025). "We determined the effects of 12-weeks supervised exercise training on the frequency of T-cell subtypes in peripheral blood and their relationships with circulating levels of the muscle-derived cytokines (i.e. ‘myokines’) IL-6, IL-7, IL-15 and osteonectin in older women at high risk of breast cancer." (PMID 35321743, 2022). "In this study, we used syngeneic IL-15/IL-12-conditioned NK cells to treat established lung metastases after resection of the primary MHC-I+ EO771 mammary tumor." (PMID 39835538, 2025). "Our experimental results confirmed that levels of IL‐15 or IL‐6 in the peripheral blood of breast cancer model mice subjected to exercise intervention were significantly elevated." (PMID 38234174, 2024). "The administration of IL-15/Rα has been shown to inhibit breast cancer growth by promoting cytotoxic CD8 T cells." (PMID 38920969, 2024). "In a murine model of breast cancer, hematopoietic and mesenchymal stromal cell sources of IL-15 are found to be dispensable for the maintenance and activity of ILC1s, while epithelial cancer cell-derived IL-15 is essential for ILC1s’ anti-tumour function." (PMID 38745765, 2024). "A study has shown mammary tumor-induced skeletal muscle dysfunction via interleukin-15 gene suppression in mice and a similar result for patients with breast cancer." (PMID 39769193, 2024). "The cytotoxic activity of extracellular vesicles-derived NK cells (NK-EVs) against breast cancer and glioblastoma can be enhanced by cytokine, IL-15." (PMID 37484408, 2023). "TRUCK CAR T-cells incorporating various soluble cytokines, including IL-15, IL-7, and IL-18, have been explored for breast cancer." (PMID 38201551, 2023). "In contrast, the receptors for IL7 (IL7R) and IL15 (IL15RA) were significantly overexpressed in basal B compared to luminal breast cancer cells." (PMID 38055067, 2023). "In colorectal cancer, IL-15 was produced by tumor cells shown by immunohistochemical analysis, and in a murine breast cancer model, IL-15 was produced by cancer cells and functioned as an alarmin." (PMID 38567059, 2023). "Further analysis are warranted to determine the contribution of IL7 and IL15 in mediating lymphatic dissemination of breast cancer cells in vivo." (PMID 38055067, 2023). "The results demonstrate the capacity of TGFβ1 to orchestrate crosstalk between tumor cells and lymphatic endothelial cells and warrant further studies to explore the roles of IL7 and IL15 in promoting lymph metastasis of breast cancer." (PMID 38055067, 2023). "In the mouse metastatic breast cancer model, high amount of metastases in IL-15−/− mice but near-abolition of tumor metastases in IL-15Tg and IL-15-treated mice compared with wild-type (WT) mice." (PMID 37251333, 2023). "IL15 was reported to affect breast cancer metastasis in mouse models by regulating the activity of natural killer cells, T cells and macrophages." (PMID 38055067, 2023). "In contrast, the receptors for IL7 and IL15 were overexpressed in breast cancer cells with basal-like, mesenchymal properties, compared to luminal cells." (PMID 38055067, 2023). "Studies have reported that the coexpression of IL15RA and IL15 in breast cancer cell lines can promote tumor cancer proliferation, prevent tumor cell apoptosis, and enhance cell migration." (PMID 35693827, 2022).
breast carcinoma (continued). "IL-15 is a cytokine that has multiple functions in regulating the adaptive and innate immune systems and tumorigenesis of lung and breast cancers." (PMID 36467072, 2022). "In metastatic breast cancer models, microwave ablation of the primary tumor inhibited tumor metastasis by activating natural killer (NK) cells via the macrophage/IL-15/NK-cell axis." (PMID 36497106, 2022). "Studies have reported that the coexpression of IL15RA and IL15 in breast cancer cell lines can promote cancer proliferation, prevent cell apoptosis, and enhance cell migration." (PMID 35693827, 2022). "In terms of the cancer microenvironment, systemic IL-15 treatment reduced tumor growth, metastasis, and recurrence by increasing the cytotoxic effects of NK cells in mice inoculated with a lung and breast cancer models." (PMID 36467072, 2022). "Others have also reported that MDSC frequencies are reduced upon IL-15/IL-15Ra administration in the Her2/neu+ mammary carcinoma." (PMID 36713398, 2022). "The data, similarly to our findings, imply that breast cancer and multiple myeloma cells are likely to reduce apoptosis and fortify themselves via autocrine IL-15 stimulation, thus becoming less dependent upon their microenvironment." (PMID 32929618, 2021). "Conversely, to reveal the exact biochemical and cellular function of IL-15 mediated stimulation in breast cancer, additional studies are needed." (PMID 32929618, 2021). "Our study has shown that in this scenario both the IL-15-producing breast cancer cell and the patients’ host immune system producing IL-15, show a pro-tumor effect and promote tumor progression and metastasis." (PMID 32929618, 2021). "In this study, we found that the serum concentration of IL-15 in breast cancer patients was significantly increased amongst those patients with poor OS and DFS and who had died at follow-up." (PMID 32929618, 2021). "Another study showed that treatment of DC vaccine pulsed with truncated neu antigen, interleukin 15 (IL-15), and IL-15Rα reduced mammary carcinoma development and inhibited HER2-dependent Akt signaling pathway in HER2/neu transgenic mice." (PMID 34899753, 2021). "In order to clarify the exact cellular mechanism of IL-15 resolved signalling in breast cancer, further studies are needed." (PMID 32929618, 2021). "Most recently, cytolytically enhanced exosomes, isolated from IL-15-treated NK-92MI cells, have been used to treat glioblastoma, breast cancer, and thyroid cancer in mice." (PMID 34368150, 2021). "This is in line with previous reports that IL-15 is an independent prognostic marker for patients with prostate cancer, breast cancer, and lung adenocarcinoma." (PMID 33668573, 2021). "Antitumor activity of IL-15 was evaluated in two murine breast cancer models, mouse Her2/neu+ and 4T1-luc mammary cancers treated with systemic administration and intratumor delivery of plasmid IL-15/IL-15Rα, respectively." (PMID 33628206, 2020). "Intratumoral GET with plasmid IL-15/IL-15Rα leads to a long-term survival benefit in 4T1 mammary carcinoma model." (PMID 33628206, 2020). "Despite very potent bioactivity of IL-15 or IL-15cx at promoting cytotoxic T/NK cells, IL-15 immunotherapy appears ineffective at destroying poorly immunogenic primary tumors such as breast cancer." (PMID 33628206, 2020). "Related to breast cancer, an Ad vector was engineered with an E2F-1 promoter and the human interleukin-15 (IL-15) gene." (PMID 33218001, 2020). "The present study proved that the novel oncolytic virus (SG400-E2F/IL-15) exhibits an enhanced anti-tumor activity both in vitro and in vivo, representing an experimental basis for breast cancer “virus-gene” therapy." (PMID 31278126, 2019). "Recently, IL-15 has been shown to inhibit the proliferation of breast cancer cells via various immune cells." (PMID 31278126, 2019).
breast carcinoma (continued). "For instance, there is observed a relapse-free survival and the inhibition of pulmonary metastasis nodules by treating with IL-7 and IL-15 after radiofrequency thermal ablation (RFA) in mammary carcinoma." (PMID 31915416, 2019). "A recent report demonstrated a role of IL-15 in anticancer immunity in that the frequencies of breast cancer metastasis were more frequent in IL-15KO mice than those in IL-15 transgenic mice or in C57BL/6 control mice." (PMID 30936185, 2019). "Poorly immunogenic TSA breast cancer tumors were treated with RT (locally in 8 Gy fractions on days 13, 14, and 15), IL-15 (2 μg/mouse daily for 10 days starting on day 12), or a combination of RT and IL-15." (PMID 31179236, 2019). "In murine mammary carcinoma, the administration of IL-7 and IL-15 after radiofrequency thermal ablation (RFA) resulted in a relapse-free survival and showed inhibition of metastatic nodules in their lungs." (PMID 25955647, 2015). "Intralesional injection with IL-7 and IL-15 in RFA-treated animals can also reduce the proportion of MDSC present in the spleen in murine mammary carcinoma." (PMID 25955647, 2015). "This study reveals that high levels of IL-15 can promote tumor destruction and reduce metastasis in breast cancer via effects on NK1.1+ cells." (PMID 25879689, 2015). "In this study, we crossed IL-15 KO and IL-15 TG mice with a spontaneous breast cancer model (MT) to create IL-15 KO/MT and IL-15 TG/MT mice." (PMID 25879689, 2015). "Here, by exploiting mice knockout for IL-15, we formally demonstrated for the first time that IL-15 sustains mammary cancer immunosurveillance." (PMID 25997501, 2015). "IL15KO/NeuT mice showed a significantly earlier mammary cancer onset than NeuT mice, with median latency times of 16 and 20 weeks respectively, suggesting a role for IL-15 in cancer immunosurveillance." (PMID 25997501, 2015). "Overall, using an orthotopic murine luminal B breast cancer model, our study identifies the immune signature of regressing tumors and the localization and in situ distribution of IL-15 complexes and anti-PD-1 mAb within immune cells in regressing and non-regressing luminal B tumors." (PMID 41373645, 2025). "To characterize the antitumor immune response in murine EO771 breast cancer induced by the two doses of intratumoral IL-15 complexes, we collected tumors at day twelve across treatment groups (two days following the second dose in groups receiving IL-15 complex treatment)." (PMID 41373645, 2025). "As well as IFN-γ, IL-15 inhibits tumors by regulation of CD8+ T cells and NK cells, but research is lacking on IL-15′s association with the induction of breast cancer metastasis." (PMID 39768997, 2024). "In addition, studies investigating the combined ablation of additional IL-2 family members have also been undertaken, injection of IL-7 and IL-15 after RFA effectively inhibits tumor growth in a mouse breast cancer model." (PMID 38833177, 2024). "Some cytokines, such as interleukin-15 (IL-15), could enhance the antitumour ability of NK cell-derived exosomes against glioblastoma, breast cancer and thyroid cancer." (PMID 38302430, 2024). "Specifically, NK-EVs primed with IL-15 have demonstrated remarkable cytotoxic activity against various human cancers such as glioblastoma and breast cancer through increasing the expression of apoptotic molecules (e.g., perforin, granzyme B, FasL, and caspases)." (PMID 37484408, 2023). "This indicated that IL7 and IL15 could act as chemoattractants for breast cancer cells with mesenchymal properties." (PMID 38055067, 2023). "The results suggested that IL7 and IL15 could function as chemotactic factors for breast cancer cells with mesenchymal properties." (PMID 38055067, 2023). "These outcomes imply a substantial function of IL-15 in the pathogenesis of breast cancer and thus could offer new insights into tumor evolution and possible therapeutic approaches." (PMID 32929618, 2021).
breast carcinoma (continued). "As the involvement of the lymphatic system is known to play a key role in the progression of breast cancer, the aim of this study was the evaluation of Interleukin 15 (IL-15) and eotaxin as markers for CTC involvement in patients with the primary diagnosis of breast cancer." (PMID 32929618, 2021). "Nevertheless, the prognostic role of IL-15 in breast cancer remains uncertain." (PMID 32929618, 2021). "In breast cancer, IL-15 provoked higher proliferation and IFNγ production of tumor-infiltrating CD8+ T cells than IL-2, and these strong but short-lived response could be diminished by the subsequently upregulated TIM-3." (PMID 33266177, 2020). "In line with this, an in vitro study in breast cancer suggested that the combination with IL-2 or IL-15 could boost the lytic activity against tumor cells, therefore augmenting the therapeutic efficacy of Avelumab." (PMID 33266177, 2020). "In addition, a novel recombinant adenovirus has been constructed that targeted E2F-1 and expressed IL-15, and validated its inhibitive effect on breast cancer cells, providing new experimental basis for breast cancer gene therapy." (PMID 31278126, 2019). "Here we will examine the anti-tumor role of IL-15 in a spontaneous breast cancer model." (PMID 25879689, 2015). "We demonstrated that IL-15 has a role in mammary cancer immunosurveillance and that IL-15-regulated NK and CD8+ memory cells play a role in long-lasting immunoprevention, further supporting the potential use of IL-15 as adjuvant in immunological strategies against tumors." (PMID 25997501, 2015). "Indeed, while some studies argue for a role of O-GlcNAcylation in the regulation of EZH2 stability and catalytic activity, others propose that the glycosylation rather regulates EZH2 recruitment to some of its target genes such as FOXC1 in breast cancer cells or IL-15 in muscle." (PMID 33126652, 2020). "We show that IL-15 complexes and anti-PD-1 therapy induce the expression of NKG2D ligand genes H60a, H60b, H60c, and Raet1a in murine luminal B breast cancer cells." (PMID 41373645, 2025). "Combination of anti-PD-L1 antibodies with the IL-15 superagonist ALT-803 (N-803) led to additive effects in murine models of colon and breast cancer." (PMID 37465665, 2023). "IL-12, IL-15, and IL-18 have demonstrated the ability to activate NK cells against hepatocellular carcinoma (HCC), melanoma, and breast cancer." (PMID 37484408, 2023). "In a recent preclinical study, IL-15 co-expression enhanced the persistence and anti-tumor activity of anti-EGFRvIII CAR T-cells in a murine breast cancer model." (PMID 38201551, 2023). "While IL15 has been shown to be associated with better prognosis in breast cancer, IL27p28 has been shown to be involved in growth and metastasis of triple-negative breast cancers and has been frequently detected in breast cancer patients but undetectable in normal women." (PMID 37503343, 2023). "Transcriptomic data from TEPA treated breast cancer cells also displays changes in the immune-related genes (including IL6, IL6R, IL15, CXCL1, CXCL8, and PTX3) in breast cancer." (PMID 37480151, 2023). "Mice with IL-15 overexpression also display higher granzyme and anti-tumoural cytokine production, suggesting IL-15/ILC1-like cell antitumor axis in breast cancers." (PMID 35557940, 2022). "The goal of this study was to examine the activity of IL-15/IL-15Rα complex (IL-15cx) to CD8+ T cells and evaluate its potential efficacy in murine breast cancer models." (PMID 33628206, 2020). "The novel SG400-E2F/IL-15 vector selectively killed tumor cells and IL-15 exhibited an immunomodulatory effect, which was confirmed in MDA-MB-231 breast cancer cells." (PMID 33218001, 2020). "Here we have examined a different strategy of IL-15 immunotherapy, intratumoral GET, in a 4T1 breast cancer model." (PMID 33628206, 2020).